ZEB1 (zinc finger E-box binding homeobox 1)
Diseases named in the same sentence as ZEB1 in open-access papers (continued):
Sharing a sentence is not in itself a finding about the gene and the disease.
melanoma (continued). "Using the cBioPortal database, we analyzed the genetic alternations of ZEB1 and CP in 1516 samples from 1477 melanoma and skin melanoma patients." (PMID 35232428, 2022). "An overlap in key regulators and stabilizers for hybrid E/M phenotypes and melanoma phenotypes (such as ZEB1, NFATC2, CDH1, SNAI2, NRF2) suggest common regulatory links." (PMID 36003764, 2022). "For example, a switch from ZEB2 to ZEB1 promotes the progression of melanoma, suggesting these two ZEB proteins function in an opposite manner under this condition." (PMID 35601657, 2022). "The KEGG pathways enriched in the high-risk group of ZEB1 including TGF-b, ECM receptor, MAPK, melanoma, and other signal pathways." (PMID 35232428, 2022). "High levels of ZEB1, correlating with Fra-1 expression and melanoma stemness markers (MITFlo/p75hi in CSCs vs MITFhi/p75lo in non-CSCs) are implicated in intrinsic resistance to BRAF and MEK inhibitors." (PMID 35326630, 2022). "We observed expressions of ferroptosis related proteins including ALOX5, PEBP1, ACSL4 and ZEB1 in melanoma, which showed a strong cytoplasmic staining." (PMID 36313708, 2022). "ZEB1-mediated T cell exclusion promotes immune evasion, as we showed that ZEB1 overexpression promotes resistance, whereas Zeb1 knock-out improves the efficacy of anti-PD-1 immunotherapy in melanoma mouse models." (PMID 35432344, 2022). "More recently, we investigated the role of the EMT-inducing transcription factor ZEB1 in immune evasion, and demonstrated its role in preventing T cell infiltration in melanoma." (PMID 35432344, 2022). "Similar as in NC-derived melanoblasts, the cadherin-switch (from E-cadherin to N-cadherin) takes place in an important subset of melanomas and is induced by ZEB1, TWIST and SNAIL." (PMID 33870460, 2021). "They found that EMT-inducing transcription factors undergo a profound reorganization in favor of TWIST1 and ZEB1 during melanoma metastatization." (PMID 33980826, 2021). "Intra-tumor heterogeneity in the expression of ZEB2/ZEB1 was also documented in the NRASQ61 melanoma mouse model." (PMID 32759677, 2020). "In melanoma context, the roles of ZEB1 and ZEB2 seem to be antagonistic and to function in line with the “phenotype-switching” model." (PMID 32796736, 2020). "After 24-h GH treatment, SK-MEL-30 human melanoma cells showed a modest but significant increase of multiple EMT-related genes including mesenchymal markers ZEB-1, SNAI1, CLDN1 and SNAI2, while the epithelial marker CDH1 was significantly downregulated." (PMID 33291663, 2020). "High levels of ZEB1/TWIST1 expression undoubtedly promote an invasive phenotype in melanoma, including decreased E-Cadherin, MITF, and increased expression of Vimentin, SPARC, and MMPs." (PMID 32759677, 2020). "Next to this, GLI family zinc finger 1 (GLI1) is proposed to be important for maintaining the invasive properties of melanoma cells in a ZEB2/MITF-independent manner but most likely ZEB1-dependent manner." (PMID 32796736, 2020). "As such, it is to be expected that some of these micro-environmental associated signalling pathways regulate melanoma plasticity through modulation of the balance between ZEB2 and ZEB1." (PMID 32796736, 2020). "Another study further demonstrates that mainly a subset of FN1high/MITFlow melanoma cells express ZEB1, which is in line with the expression of the hypoxic marker hypoxia inducible factor 2 subunit alpha (HIF2A) and stem cell markers NGFR and JARID1B." (PMID 32796736, 2020). "Based on our previous results that implicated RKIP on the migration capability of melanoma cells, we made use of RKIP overexpression to analyze the effect on ZEB1, NTRK2, and THY-1 transcription." (PMID 32503139, 2020). "Both MAPKi-resistant BRAFV600E-mutated melanoma cell lines and tumour biopsies obtained from human MAPKi-resistant BRAFV600E patients express high levels of ZEB1 but low levels of ZEB2 and MITF." (PMID 32796736, 2020).
melanoma (continued). "In particular, a reduced expression of ZEB2 and SNAIL2 in favour of an increased expression in ZEB1 and TWIST1 was linked to E-cadherin loss, increased invasion properties and poor clinical outcomes in human melanoma." (PMID 32858889, 2020). "NFATc2 showed a positive correlation with AXL, SNAI1, CDH2, and ZEB1 even in the TCGA melanoma dataset." (PMID 30710146, 2019). "The correlation in expression between GPC6 and ZEB1 is evident within each of the four categories of melanoma." (PMID 31199813, 2019). "The switch between Zeb2 and Zeb1 inside the melanoma was observed to be correlated with reduced expression of MITF and consequently with tumor progression." (PMID 31934531, 2019). "Expression of NFATc2, MITF, AXL, ZEB1, SNAI1 (encoding SNAIL), and CDH2 (N-Cadherin) was then evaluated at the mRNA level, by qPCR, in a larger panel of 30 melanoma cell lines." (PMID 30710146, 2019). "ZEB1 expression was higher in metastatic melanoma (cutaneous/subcutaneous, lymph node, or distant metastases) compared to primary melanoma." (PMID 31199813, 2019). "Analysis of the two distinct melanomas found in radial growth phase, either driven by Mitf or EphrinA3, determined zinc finger E-box-binding homeobox 1 (Zeb1) to be a driver of the unpigmented state." (PMID 29762513, 2018). "This is further supported by the observation that expression of the EMT inducing transcription factor ZEB1 is increased in MAPK-inhibition surviving melanoma cells." (PMID 29716947, 2018). "The master regulator of melanoma cell proliferation is the MITF/ZEB-1 couple of transcription factors." (PMID 29973136, 2018). "For example TWIST1 and ZEB1 increase the metastatic potential of melanoma cells whereas SNAI2 (SLUG) and ZEB2 decrease it." (PMID 29432466, 2018). "Other studies have shown that Slug regulates Zeb1 expression in melanoma at transcriptional level through binding to the E-boxes of promoter." (PMID 28137308, 2017). "In melanocytes, the expressions of Snail2 and Zeb2 were found to be higher and act as oncosuppressor whereas Twist1 and Zeb1 promote neoplastic transformation of melanocytes and aberrantly reactivate in melanoma." (PMID 28137308, 2017). "Knocking down of Zeb2 leads to significant downregulation of MITF and concomitant upregulation of Zeb1, Vimentin and Fibronectin resulted in enhanced melanoma progression." (PMID 28137308, 2017). "To investigate the putative role of ZEB1 in the development of acquired resistance to BRAFi, we established two lines of BRAFi‐resistant melanoma cells." (PMID 27596438, 2016). "We herein uncovered the role of the EMT‐inducing transcription factor (EMT‐TF) ZEB1 as a major driver of phenotype switching in melanoma cells, providing them with a resistance to MAPKi." (PMID 27596438, 2016). "Collectively, 50% of primary resistant melanomas exhibited a strong staining for ZEB1 and/or TWIST1." (PMID 27596438, 2016). "ZEB1 levels are also elevated in melanoma cells with acquired resistance and in biopsies from patients relapsing while under treatment." (PMID 27596438, 2016). "Overall, our results demonstrate that ZEB1 is a major driver of melanoma cell plasticity, driving drug adaptation and phenotypic resistance to MAPKi." (PMID 27596438, 2016). "Collectively, these data highlight the role of ZEB1 as a major driver of phenotype switching in melanoma cells, providing them with a resistance to MAPKi." (PMID 27596438, 2016). "Altogether, an inverse correlation was observed between ZEB1 and MITF levels in BRAFV600‐mutated melanoma at the intra‐tumoral level, and this ZEB1high/MITFlow profile showed a trend toward intrinsic resistance to MAPKi." (PMID 27596438, 2016). "High levels of ZEB1 expression undoubtedly promote an invasive phenotype in melanoma, including decreased E‐cadherin and increased expression of Vimentin, SPARC, and MMPs." (PMID 27596438, 2016). "This prompted us to investigate how ZEB1 promotes intrinsic or acquired resistance to MAPKi in BRAFV600‐mutant melanoma." (PMID 27596438, 2016).
melanoma (continued). "ZEB1 inhibition promotes cell differentiation, prevents tumorigenic growth in vivo, sensitizes naive melanoma cells to MAPKi, and induces cell death in resistant cells." (PMID 27596438, 2016). "Overall, these data demonstrate that ZEB1 knockdown decreases the viability of resistant melanoma cells in both MITFlow (RPMI7951, A375‐R, GOKA) and MITFhigh (SKMEL5‐R, ESP) cellular contexts." (PMID 27596438, 2016). "ZEB1 inhibition was shown to increase sensitivity to MAPKi, prevent the emergence of resistance, and induce cell death in various melanoma cells with intrinsic or acquired resistance to BRAFi." (PMID 27596438, 2016). "We further demonstrated that ZEB1 overexpression in melanoma cell lines triggered the emergence of resistance to MAPKi by promoting the reversible conversion of a MITFhigh/p75low differentiated state into a MITFlow/p75high stem‐like and tumorigenic state." (PMID 27596438, 2016). "Indeed, one of the roles of ZEB1 is to regulate the expression of E-cadherin, a key molecule in the maintenance of epithelial cell characteristics, as its loss may enhance the invasive and metastatic behavior of melanoma cells." (PMID 27764776, 2016). "Our findings demonstrate that the ZEB1 transcription factor is a key determinant of melanoma phenotypic plasticity, tumorigenicity, and resistance to MAPKi, by fostering the adaptation to the therapeutic drugs." (PMID 27596438, 2016). "In melanoma cells, Slug also acts as a direct transcriptional activator of E-box at the ZEB1 promoter, and cooperatively repressed E-cadherin expression resulting in increased migration and metastasis of melanoma cells." (PMID 26517521, 2016). "Thirty percent of primary resistant melanomas exhibited high levels of endogenous ZEB1, compared to only 7.5% of the initially responding tumors (P = 2.27E‐2)." (PMID 27596438, 2016). "Using linear regression analysis, miR-33b displayed a significant negative correlation with the expressions of HMGA2, Twist1 and ZEB1, consistent with these genes being regulated by miR-33b in melanoma." (PMID 25868853, 2015). "In melanoma, overexpression of ZEB1 and TWIST1 with low expression of ZEB2 significantly shortens metastasis-free survival." (PMID 26515895, 2015). "SLUG was also identified in melanoma cell lines as a direct transcriptional activator of ZEB1, resulting in repression of E-cadherin." (PMID 25763355, 2015). "In agreement with western blotting results, immunofluorescence staining suggested that miR-33b silencing or ZEB1 overexpressing reverted cordycepin-mediated epithelial differentiation of melanoma cells." (PMID 25868853, 2015). "The negative correlations between miR-33b levels and HMGA2, Twist1 or ZEB1 expression were detected in 72 patient melanoma tissue samples." (PMID 25868853, 2015). "We showed for the first time that targeting miRNA by cordycepin indicates a new mechanism of cordycepin-induced suppression of tumor metastasis and miR-33b/HMGA2/Twist1/ZEB1 axis plays critical roles in regulating melanoma dissemination." (PMID 25868853, 2015). "Recent research showed that a reversible EMT-TF (transcription factor) reprogramming involving upregulation of ZEB1/TWIST1 paralleled by downregulation of SNAIL2/ZEB2 occurs in human melanoma." (PMID 25051363, 2014). "In the present study, our goal was to use a tumor vaccine B16F10/GPI-IL-21 in combination with regulation expression of miR200c and ZEB1 against melanoma, an aggressive skin cancer that there is no cure in advanced stages until now." (PMID 24625224, 2014). "To elicit a potent antitumor efficacy against melanoma, we used tumor vaccine in combination with miR200c overexpression or ZEB1 knockdown to assess the efficacy of treatment of murine melanoma." (PMID 24625224, 2014). "The detection of ZEB1 protein in melanocyte stem cells further implicates a TGF-β-ZEB1 circuitry relevant to both melanocyte and melanoma stemness." (PMID 25538895, 2014).
melanoma (continued). "Moreover, MAPK pathway activation induces FRA1 in melanoma cells, which promotes transcription factor reprogramming, favoring ZEB1 and TWIST1 expression, transcription factors that induce EMT-like states." (PMID 41286309, 2025). "Furthermore, our findings that KPC1 acts upstream to control ZEB1 stability align with and provide a novel regulatory mechanism for previous studies highlighting ZEB1 as a central mediator of invasive and therapy-resistant melanoma states." (PMID 41429767, 2025). "Indeed, melanoma cells can undergo “neural crest-like reprogramming,” marked by a switch from E-cadherin-high to zinc-finger E-box-binding homeobox 1 (ZEB1)-high states, closely mimicking EMT dynamics." (PMID 41462674, 2025). "The results of this study extends the current mechanistic models of transcriptional and epigenetic control of melanoma phenotypic switching, to demonstrate that ubiquitin–proteasome–mediated regulation of ZEB1 protein stability represents a critical and underexplored layer of control." (PMID 41429767, 2025). "While no enrichment in the activity of the conventional ZEB1 regulon was observed, we could show an increase in the melanoma-specific ZEB1.mel regulon in these models." (PMID 38519642, 2024). "Overall, our results define ZEB1 as a major transcriptional regulator of cell states transitions and provide a better understanding of lineage-specific transcriptional programs sustaining intra-tumor heterogeneity in melanoma." (PMID 38519642, 2024). "The transcription factor ZEB1 is a known inducer of mesenchymal–epithelial transition and invasiveness; in melanoma, elevated ZEB1 levels are associated with resistance to treatment with MAPK inhibitors, while the ZEB1/ZEB2 ratio would mediate phenotypic plasticity." (PMID 39594467, 2024). "The results showed that as the melanoma progressed, the expression of malignant progression marker genes (pmel, mlana, sox10, cdk4, zeb1, and vim) significantly increased, with notable expression differences observed among benign nevi, dysplastic nevi, and invasive melanoma." (PMID 39659584, 2024). "Herein, in order to characterize ZEB1 function and provide a comprehensive view of its transcriptional target genes in a genome-wide manner, we performed ChIP-sequencing combined with RNA-sequencing upon phenotype switching in melanoma cells." (PMID 38519642, 2024). "Finally, we evaluated the Tspan8 expression level in patient melanomas by immunohistochemistry according to the ZEB1 expression level, between ZEB1high, ZEB1int, and ZEB1low melanomas, in a cohort of 18 patient samples." (PMID 38398085, 2024). "In melanoma, we previously showed that, during melanoma progression, a switch in the EMT-TFs’ expression occurs, with a loss of ZEB2 and SNAI2 expression and the upregulation of ZEB1 and TWIST1 expression." (PMID 38398085, 2024). "Epithelial to mesenchymal transition (EMT)-like processes enable melanoma cells to disseminate from the primary site and this is orchestrated by the main transcription factors Snail, Slug, ZEB1 and Twist1, whereas their repression is required to promote metastatic growth in vivo." (PMID 38419052, 2024). "Of note, based on the microscopic analysis of mouse skin xenografts of SN-MM cells, we could identify a proliferation of MITFlow/CDH1−/CDH2+/ZEB1+/CD271+ melanoma cell clusters losing most melanocytic markers, thus suggesting a MIC identity, as proposed in CM." (PMID 38191367, 2024). "Although targeting ZEB1 remains challenging, this work highlights new candidates/pathways that could represent interesting targets to dampen melanoma cell plasticity as a strategy to overcome treatment resistance." (PMID 38519642, 2024). "A gain in ZEB1 expression could be observed not only at the invasive front of primary melanomas, but also in the bulk, either in specific clones (as in MM10) or in the whole tumor (as in MM14)." (PMID 38519642, 2024).
melanoma (continued). "Though direct target genes of ZEB1 have been characterized in carcinoma models, they remain unknown in melanoma." (PMID 38519642, 2024). "ZEB1 and other melanoma markers of intra-tumor heterogeneity may thus significantly be modified by the tumor microenvironment in specific niches that will deserve further characterization." (PMID 38519642, 2024). "We accordingly found that inducing melanoma EMT switching by overexpressing the ZEB1 transcription factor, a major regulator of melanoma cell plasticity, was sufficient to decrease cell stiffness and transcriptionally induce tetraspanin-8-mediated dermal invasion." (PMID 38398085, 2024). "In contrast, melanoma cell invasion was driven by high ZEB1 and low ZEB2 expression levels." (PMID 38139138, 2023). "Moreover, dependency on GPX4 exists across diverse therapy-resistant states characterized by high expression of ZEB1, such as TGFβ-mediated therapy resistance in melanoma." (PMID 37024452, 2023). "In particular, Fra-1 (encoded by the gene FOSL1) is important for melanoma progression as its accumulation triggers the transcription factor switch that drives (partial)-EMT, downregulating Zeb2 and SNAI2 and directly upregulating Zeb1 at its promoter." (PMID 37181747, 2023). "This ‘switch’ in cadherin expression is driven by downregulation of the EMT transcription factors (EMT-TFs) Snail and Zeb1 and correlates with a low proliferation rate and acquisition of an invasive phenotype in melanoma cells." (PMID 37181747, 2023). "Indeed, a recent study has revealed a novel role for ZEB1, indicating its involvement as a driver of lineage-specific transcriptional programs that regulate cellular state transitions in melanoma." (PMID 37511550, 2023). "Previous studies revealed that during melanoma progression, melanoma cells develop stem-cell like properties associated with the expression of SOX10, EZH2 transcription factors, EMT phenotypic switch regulators TWIST1/ZEB1, and the surface receptor CD172." (PMID 35269844, 2022). "ZEB1 and CP were altered in 10% and 7% of the queried melanoma samples, respectively." (PMID 35232428, 2022). "Whether ZEB1/EMT-TF specific expression by melanoma cells may predict response to ICB in patient cohorts remains to be addressed." (PMID 35432344, 2022). "Indeed, one of the transcriptional targets of Slug is the ZEB1 protein, which is capable of directly activating the transcription of N-cadherin and vimentin in melanoma." (PMID 36429073, 2022). "Interestingly, high KDM5B/JARID1B expression was previously reported in slow cycling therapy-resistant melanoma cells, and it is known that ZEB1 induces the upregulation of JARID1B in melanoma." (PMID 35432344, 2022). "Then we discovered and analyzed the effects of CP and ZEB1 in melanoma patients." (PMID 35232428, 2022). "In the melanoma samples, ZEB1 level was positively related to CD4+ T cells (R = 0.338, p = 1.20e−13), CD8+ T cells (R = 0.203, p = 1.17e−5), macrophages (R = 0.152, p = 1.12e−03), dendritic cells (R = 0.008, p = 8.67e−1) and neutrophils (R = 0.528, p = 3.15e−34)." (PMID 35232428, 2022). "Next, we discussed the immune infiltration level of ZEB1 and CP in melanoma." (PMID 35232428, 2022). "Thus, female melanoma cells with high expression of ERβ show a reduction in N-Cadherin, vimentin, Snail, and Zeb1 and characteristically a parallel increase in PTEN expression; while in the ERβ silencing experiments, markers of EMT rise and PTEN decreases." (PMID 36499700, 2022). "Besides, ZEB1 reverses the more primitive state of melanoma (a neural crest stem cell (NCSC)) into a more differentiated state and reduces drug resistance to related treatments." (PMID 36313708, 2022). "In addition, ZEB1 is overexpressed in melanoma cells with acquired drug resistance and in biopsies from patients relapsing while under treatment." (PMID 35326630, 2022).